CTLA4 (cytotoxic T-lymphocyte associated protein 4)
Diseases named in the same sentence as CTLA4 in open-access papers (continued):
Sharing a sentence is not in itself a finding about the gene and the disease.
tumor (continued). "Such agents in current use include monoclonal antibodies against three key targets: immune checkpoints PD-1 and CTLA-4, which enhance tumor-killing T cell immune functions; pro-angiogenic factor VEGF; and integrin adhesion molecules that mediate interactions between tumor cells and the TME matrix." (PMID 35002732, 2021). "Resultantly, the combination of CTLA4 antibody with lipofermata in LLC-bearing mice caused a potent antitumor effect, where the administration of each monotherapy failed to block tumor progression." (PMID 35003065, 2021). "Therefore, approximately 2 months after Lm-based vaccination, mice were challenged with tumor, and received ICI (either anti-PD-1, anti-CTLA-4, or anti-PD-L1) every 10 days subsequently, in order to maintain anti-tumor T cell function." (PMID 33936058, 2021). "The mechanisms by which HIF-1 suppresses the function of effector T-cells are complex, but include the upregulation of co-inhibitory receptors (e.g., CTLA-4 and LAG-3), the differentiation of CD4+ T-cells into Tregs and the indirect effect of altered tumour cell metabolism." (PMID 33923305, 2021). "Another study tested combination therapy of anti-CTLA-4 with RT and demonstrated that this strategy not only depleted Treg (by anti-CTLA-4) but also promoted the diversity of TCR repertoire of TILs (by RT), resulting in potent anti-tumor responses." (PMID 34830176, 2021). "Interestingly, combination treatment with anti-CTLA4 further enhanced the anti-tumor effect and significantly inhibited tumor growth compared with ICB alone in various tumor models." (PMID 35011582, 2021). "Next, we tested the efficacy of co-administration of α-IL-6 and α-CTLA-4 on lung orthotopic model in which LLC cells were inoculated percutaneously into the left lateral thorax, and the tumor nodules in the right lungs of injected mice were considered as metastatic lesions." (PMID 34093869, 2021). "Although doxorubicin showed a trend to decline the level of expression of CTLA-4 in 4T1 tumor tissue, no statistically significant alterations were evident among groups." (PMID 34094037, 2021). "While IL-6 neutralization has been shown to enhance T cell tumor infiltration, it alone does not sensitize the tumor to immune checkpoint blockade via anti-PD-1 or anti-CTLA-4." (PMID 34976006, 2021). "Compared to the effects of the inhibitors of the function of CTLA-4, PD-1, and/or HSP90 used alone or in combination with each other, additional treatment with WBI appeared to be clearly more efficient in suppressing the CC of the lung-derived tumor cells." (PMID 34208396, 2021). "CTLA-4 binds to costimulatory molecules CD80 and CD86 on DCs and thus blocks their binding to CD28 on T cells, resulting in inhibition of the costimulatory signals necessary for the induction of tumor-specific T cell responses." (PMID 34885241, 2021). "We, therefore, assume that PD-L1 on tumor cells did not effectively control the CTLA-4/CD80 axis in TC-1- and TC-1/dCD80-1-induced tumors." (PMID 33923750, 2021). "Once T cells have infiltrated a tumour, MHC-I, ICAM-1, RAE-1γ and NKG2D promote T cell arrest, tumour cell engagement and were found to be essential for the efficacy of a combination of radiotherapy and CTLA-4 blockade in mice." (PMID 33499003, 2021). "PD-1 and CTLA4 are the most extensively studied immune-checkpoint negative regulators due to their prominent role in fine-tuning tumor-infiltrating T cells." (PMID 34897277, 2021). "While anti-CTLA-4 therapy acts mainly on CD4 during the antigen presentation, anti-PD-1 is more effective at restoring the effector function of exhausted CD8+ T cells to clear tumor cells." (PMID 34572799, 2021). "CTLA-4 expressed by T cells can also inhibit the activity of CD8+ T cells and tumor immunity." (PMID 34326840, 2021).
tumor (continued). "This intense immune response would be hampered by some therapy‐sensitive mechanisms, such as PD‐1+ and Tregs, but not by CTLA‐4+ or determined inhibitory cytokines, that after chemoimmunotherapy would lead to complete tumor elimination." (PMID 34323406, 2021). "Indeed, combining mTORC1/mTORC2 inhibitor vistusertib with different immune-checkpoint blockades, including anti-PD-1, anti-PD-L1 or anti-CTLA-4, significantly reduced MC38 or CT-26 tumor growth compared to monotherapies." (PMID 33802831, 2021). "Following treatment with PD-1 blockade, CTLA-4 blockade, or OX40 stimulation, we observed inter-individual variability in the response to therapy between genetically identical animals bearing the same tumor." (PMID 34221953, 2021). "Another study was done to see if the link between CTLA-4 monoclonal antibodies and the gut microbiota was the same as in anti-PD1 treatment, and it was observed that Bacteroidales play a crucial role in the effects of CTLA-4 inhibition on tumor immunity." (PMID 34681948, 2021). "Entinostat (histone deacetylase inhibitor) eradicates 80% of tumour cells and reduces MDSCs in combination with anti-CTLA4 and anti-PD1 antibodies, where monotherapy with ICIs has not achieved responses." (PMID 33925214, 2021). "Clinical studies demonstrate that CD4 T cells with anti-tumor reactivity can mediate their effects via direct cytotoxicity against tumor targets, and by broadening the CD8 T-cell response in the context of immunotherapy, such as with anti-CTLA-4 antibodies." (PMID 34201655, 2021). "Besides these observations in human samples, the blockade of CTLA-4 in an immune-competent mouse model of HNSCC significantly reduced MDSCs, M2 macrophages, and tumor burden while improving the effector function of T cells." (PMID 33804419, 2021). "PD-L1, CTLA-4, TIM3, ARG1, and EBAG9 have been confirmed to exist in exosomes and may be involved in the regulation of tumor progression." (PMID 34743730, 2021). "In addition, tumor cells produce VEGF-A, which can increase the expression level of PD-1, CTLA-4, and TIM-3 in CD8+ T cells, thereby inducing T-cell exhaustion." (PMID 34961815, 2021). "Disruption of this negative feedback using anti-PD-1, anti-PD-L1, or anti-CTLA4 antibodies reactivates T-cell cytotoxic properties which effectively lead to tumor antigen-specific immune responses and tumor killing." (PMID 33494181, 2021). "MAIT cells with their increased expression of PD-1, CTLA-4 and TIM-3 in cancer may be targets for immune-checkpoint inhibitor therapy, potentially restoring MAIT cells anti-tumour abilities." (PMID 33808058, 2021). "In addition, other checkpoints have also been knocked out through gene editing technology to improve the anti-tumor activity of CAR-T cells, such as CTLA-4, TIM-3, and LAG-3." (PMID 33728333, 2021). "CTLA-4 can inhibit the proliferation of self-reactive T cells rather than tumor-specific T cells by binding to B7 to competitively inhibit CD28 co-stimulation." (PMID 34367975, 2021). "Unlike PD-1/PD-L1 inhibitors, the using of CTLA-4 inhibitors would like to relieve the inhibitory effect of regulatory T cells (Treg) in the tumor microenvironment, enhancing the body’s tumor immunity to eliminate tumor cells in the body." (PMID 35069586, 2021). "The TCF1high T cells can be efficiently rescued and acquire a stronger effector profile and anti-tumor activity by the treatment with IC inhibitors (e.g., anti-PD-1, anti-PDL-1, anti-CTLA-4 mAbs), or the combination of the latter with vaccine therapy containing mutated tumor neo-antigens." (PMID 35069600, 2021). "From a unique tumor microenvironment that favors the growth and survival of GBM cells to the usage of immune checkpoint molecules such as PD-L1, CTLA-4, and T-cell Ig and mucin domain 3 (TIM-3), GBM thrives and develops explaining its characteristic high replication." (PMID 35103180, 2021).
tumor (continued). "Anti-CTLA-4 alone decreased tumor growth rate, but did not lead to the regression of primary or distant tumors." (PMID 33537087, 2021). "For instance, DNA methylation levels in gene promoters, and genome-wide methylation levels play important roles in PD-1, PD-L1, PD-L2, and CTLA-4 gene expression, as well as in CD8+ T cell exhaustion, tumour-specific immune cell recruitment, impairment of T cell expansion and clonal diversity." (PMID 34968365, 2021). "When this treatment was repeated with larger tumors (tumor size ≥ 15 mm2 at treatment initiation), the combination therapy did not improve anti-CTLA4 efficacy." (PMID 33123754, 2021). "CTLA-4, a checkpoint for tumor immunotherapy, can induce T cells to be nonreactive and participate in the repression of T cell proliferation, cell cycle progression, and the immune response." (PMID 33867351, 2021). "Subsequent studies demonstrated significant anti-tumor responses without overt immune toxicities, when the mice bearing partially immunogenic tumors were treated with CTLA4 antibodies." (PMID 34094935, 2021). "The costimulatory molecule cluster of differentiation (CD) 80, which can be expressed on antigen-presenting cells (APCs) or tumor cells, interacts with both costimulatory (CD28) and coinhibitory (cytotoxic T-lymphocyte antigen 4 (CTLA-4)) receptors and regulates the immune response." (PMID 33923750, 2021). "Furthermore, 72h after irradiation, a decrease in PD-L1 and CTLA-4 expression were observed, as well as an increase in CD8+ T cell activity after their interaction with tumor cells." (PMID 34595122, 2021). "Last, a less studied immune cell population in the context of anti-tumor immunity are the eosinophils, which were recently shown in a murine model of HCC to promote tumor-cell killing through degranulation and contribute to the efficacy of the anti-PD1 + anti-CTLA4 combination immunotherapy." (PMID 33815418, 2021). "Importantly, POLD1 expression was associated with immune checkpoint molecules, including CD274, CD80, CD86, CTLA4, PDCD1 and TCGIT, and facilitated an immune-excluded tumor microenvironment." (PMID 34868924, 2021). "While BEMPEG and anti-CTLA-4 alone do not control established primary tumors in this model, this combination of immunotherapy does augment local tumor control when combined with moderate dose hypo-fractionated RT or surgery." (PMID 33937052, 2021). "Compared with RT, the therapeutic outcome of RT+anti-CTLA-4 and RT+anti-PD-1 was significantly better, while RT+anti-PD-L1 did not improve tumor response." (PMID 33688020, 2021). "In MC38-B6/lpr mice treated with anti-PD-1 and anti-CTLA-4 antibodies the discrimination between responders and non-responders was determined by observing the segregation of the tumor growth curves between both populations." (PMID 33571254, 2021). "The immunosuppressor CTLA-4 (expressed on T helper cells) was variably modulated by RT, decreasing (DU145), increasing (LNCaP), or insignificantly increasing (PC3) in three different tumor cells lines." (PMID 34830179, 2021). "This cross-reactivity of microbes with tumor antigens influences anti-cancer immunotherapy as well, as CD4+ and CD8+ T cells specific for microbial epitopes are necessary for the efficacy of anti-PD1 and anti-CTLA4 therapies." (PMID 33708214, 2021). "Meanwhile, percentages of regulatory T cells (Tregs) and expression of CTLA‐4 were both up to two‐fold higher in the RAPA group, suggesting the inconsistent reactivation potential of the FK506 and RAPA groups when an anti‐tumour or anti‐infection immune response is concerned." (PMID 34841735, 2021). "Accordingly, blocking the binding of CTLA4 and CD80 could specifically eliminate these tumor-initiating stem cells and inhibit tumor relapse after immunotherapy." (PMID 34722635, 2021). "ICBs can decrease the negative immunomodulation exerted by tumor cells/Tregs through PD-1/PD-L1 and CTLA-4/B7-1, B7-2 pathways and thus restore antitumor effects of T cells." (PMID 34134781, 2021).
tumor (continued). "The polyclonal activation of T cells in the periphery induced by anti-CTLA-4 was however shown to correlate with treatment-related auto-immune toxicity rather than with tumor response in both preclinical models and human studies." (PMID 33602280, 2021). "The strategy of blocking CTLA4 was questioned because of lack of tumor specificity to the expression of CTLA4 ligands and because of the dramatic lethal autoimmune and hyperimmune phenotype of CTLA4-knockout mice." (PMID 34094935, 2021). "The HBV infection–related HCC immunosuppressed tumor microenvironment features upregulation of PD-1 in CD8+ T cells; long-lasting inhibition of Tregs via higher levels of IL-10 and TGF-β secretion; and the co-inhibitory signal of LAG3, TIM-3, and CTLA-4." (PMID 32547550, 2020). "CTLA4 has been shown to outcompete T cell co-stimulatory receptor, CD28 to bind CD80 and CD86 ligands, and creating an immunosuppressive environment which is conducive to tumor growth." (PMID 33240859, 2020). "The co-expression of PD1, CTLA4, LAG3, and TIM3 were more commonly observed in tumor tissues compared with normal tissues, which may explain the limited effects of a single immune checkpoint inhibitor and the use of combined strategies." (PMID 32728493, 2020). "These include tumour promoting molecules such as VEGF to provide anti-angiogenic therapy (e.g., bevacizumab), IL-6, and MIF (macrophage migration-inhibitory factor), immune checkpoint inhibitors (e.g., PD-1 and CTLA-4), as well as TAAs, e.g., HER2." (PMID 32937961, 2020). "Additionally, the authors showed that their nanoparticle formulation, combined with CTLA-4 checkpoint blockade therapy and radiotherapy, could inhibit tumor metastases and provide long-term antitumor immunity effects when rechallenged by an additional tumor inoculation." (PMID 33260534, 2020). "By preventing B7 and CD28 ligation, CTLA-4 suppresses signal 2 in the antigen presenting cell—T cell interaction thereby leading to T-cell suppression; in this setting, anti-CTLA-4 releases this checkpoint, resulting in enhanced anti-tumor immunity." (PMID 32784389, 2020). "However, efficient tumor eradication by the immune system is countered by elevated PD-L1 expression by MSI-H CRC cells and elevated PD-1 and CTLA-4 by effector T-cells." (PMID 32575843, 2020). "However, HLA-related gene expression promotes immune responses to clear tumors, while immune checkpoint genes (PDL1, CTLA4, TIM-3, and CD276) suppress immune responses and facilitate tumor proliferation and metastasis." (PMID 33391355, 2020). "Alternatively, anti-CTLA-4 antibodies may be complemented by the stimulator of interferon genes (STING) agonists that promote intratumoral T-cell infiltration and sensitize tumor cells to NK cell killing." (PMID 33256070, 2020). "Mice immunised with (MS@OVAinMOF)@(anti-CTLA4inMOF) show a higher ratio of tumour-free mice, significantly higher survival rate, and significantly smaller tumour volume than those administrated with (OVAinMOF)@(anit-CTLA4inMOF), free OVA-anti-CTLA4, and only saline." (PMID 32737343, 2020). "We and others have previously reported that anti-CTLA-4 antibodies, including Ipilimumab selectively depleted Treg in the mouse tumor microenvironment but not in the spleen." (PMID 31991588, 2020). "Recent study showed that the MEK inhibitors selumetinib could be a complement for anti-CTLA-4 therapy to negate the upregulation of COX-2 and ARG1 in the tumor after the neutralization of CTLA-4." (PMID 32508809, 2020). "Neither CD80 nor CD86 are expressed on non-haematological tumour cells, so the main effects of CTLA-4 are thought to occur within the secondary lymphoid organs." (PMID 32937961, 2020). "In another study, the same group used the B16F10-OVA tumor model and treated them with DNA vaccines encoding OVA (pOVA) or IL-12 (pIL-12), with or without CTLA-4 or PD-1 blockade." (PMID 33008010, 2020).
tumor (continued). "Not surprising, the MUC1 vaccine combined with anti-CTLA-4 monoclonal antibody can induced more tumor-infiltrating CD8+ T cells than single treatments." (PMID 32408880, 2020). "Although our signature was negatively correlated with tumor-infiltrating immune cells and PD-1 and CTLA-4, the correlation was not very significant." (PMID 32143735, 2020). "Somewhat paradoxically, high HIF2A expressing tumours also displayed general upregulation of CD8 T-cell scores and some NK cell scores and downregulation of all three scores for regulatory T cells and for the immune checkpoint proteins PD-1 and CTLA4." (PMID 32807776, 2020). "Besides PD-1, immune cells can express other inhibitory receptors such as CTLA-4, T-cell immunoglobulin 3 (TIM-3), ITIM domain protein (T-cell immunoglobulin and ITIM domain, TIGHT) to mediate tumor immune resistance." (PMID 32850400, 2020). "In addition, the importance of PD-1 and CTLA-4, TIM-3, CD160, and CD244 in promoting tumor growth and progression has been reported in preclinical models." (PMID 32393998, 2020). "Since CTLA-4 is expressed at high levels by Tregs, one of the actions of anti-CTLA-4-antibodies may be to downregulate Tregs in the tumor microenvironment." (PMID 33374927, 2020). "When the PD1/PD-L1 pathway blockade is combined with stimulatory anti-OX40, or with anti-CTLA-4 and anti-CD137, ID8-tumor bearing mice achieve a prolonged survival, and exhibit an increased CD8+ and Foxp3-CD4+ T-cell-to-Treg ratio, as well as a reduction of MDSC." (PMID 32630708, 2020). "In the spleen tissue, the expression intensity of the PD-1 increased with the tumor growth, unlike the expression of CTLA-4 in each subpopulation, which decreased with tumor growth (* P < 0.05)." (PMID 32805718, 2020). "In addition, CARs targeting EIIIB modified to secrete anti-CTLA-4 single-domain antibodies showed decreased expression of PD-1 and PDL-1 on the CAR T cells and improved persistence in an immune-competent tumor model." (PMID 32764348, 2020). "Considering the role of CTLA-4 in potentiating immune responses against cancer cells, and the new evidences suggesting the role of EGFR not only in the survival of tumor cells but also in the inhibition of immune system, we investigated the effects of the immunoconjugate also on the immune cells." (PMID 32024070, 2020). "Disease recurrence was associated with increase of total exosome proteins, after ipilimumab therapy, total exosome protein and tumor-derived and/or T-cell derived exosomes levels decreased, CD3+ and CD3+ CD15s+ exosomes stabilized and CD3+ CTLA4+ exosomes declined." (PMID 31935901, 2020). "Recent studies showed that the single A2AR blockade or the combination with either PD-1/PD-L1 or CTLA-4 mAbs induces T-cell proliferation, enhances the expression of IFNγ and granzyme B by tumor-infiltrating CD8+ T-cells, thus restraining the tumor growth in preclinical models." (PMID 32760402, 2020). "Treatment-induced depletion of Foxp3+/CTLA4+ Tregs was only seen in tumor samples, but not in the peripheral blood." (PMID 32681091, 2020). "Consistent with previous studies, CTLA-4 mAbs failed to control tumor growth, and tumoral expression of IL36 had pronounced antitumor functions." (PMID 32351508, 2020). "In a prophylactic vaccination schedule, CTLA-4 blockade significantly boosted expansion of Ag-specific CD8+ T-cells, which translated into strengthened antitumour immunity with systemic reduction of metastatic tumour burden." (PMID 33121210, 2020). "Additionally, the Tumor Immune Dysfunction and Exclusion (TIDE) algorithm and GDSC analysis suggested the IPM-low as a promising responder to anti-CTLA-4 therapy and the common FDA-targeted drugs, while the IPM-high was non-responsive to these treatments." (PMID 33585439, 2020).